STAT3 (signal transducer and activator of transcription 3)
Diseases named in the same sentence as STAT3 in open-access papers (continued):
Sharing a sentence is not in itself a finding about the gene and the disease.
cancer (continued). "In this study, we found that overexpression of HMGA2 in cancer cells promoted macrophage recruitment and M2 polarization in TME by upregulating signal transducer and activator of transcription 3 (STAT3)-mediated CCL2 secretion in CRC, as evidenced by in vivo and in vitro experiments." (PMID 34976223, 2022). "Furthermore, deactivation of the key signaling pathways involved in cancer progression such as NF-κB, ERK1/2, p38, STAT1, STAT3, STAT5 was also evaluated by this technique." (PMID 36230847, 2022). "Therefore, its potential as a therapeutic target for cancer has been indicated; furthermore, the antitumor effect of inhibiting the JAK/STAT3 pathway, which is the main signaling pathway of IL-6, has been reported." (PMID 35089951, 2022). "Until very recently, STAT3 and STAT5 were probably the STAT family members with the most significant role in cancer development, in particular STAT3, as it clearly turned out to be the most thoroughly investigated STAT protein in cancer research." (PMID 35163491, 2022). "Overall curcumin (non-analogue) has been shown to reduce STAT3 activation in both immune and cancer cells and potentiate anticancer immunity." (PMID 36700235, 2022). "STAT3 pathway is reported to regulate the EMT and CSC in cancer development." (PMID 35356799, 2022). "While cytokine receptors are activated, STAT3 is phosphorylated at Tyr705, leading to the nuclear translocation of activated STAT3 and the induction of downstream target genes such as CCL2 that promote various cellular processes for cancer progression." (PMID 36547079, 2022). "In cancers where high Src is the driver, Src inhibition would increase, rather than decrease, Stat3 activity, with a worsening in the clinical picture as a result." (PMID 36010614, 2022). "Compounds 6 and 16, which showed antiproliferative activity against a panel of cancer cell lines with IC50 values in the low μM range, were tested as tubulin polymerization inhibitors (similarly to TUB015) and as STAT3 inhibitors, using niclosamide as a reference compound." (PMID 35890135, 2022). "However, we found that CCL5-activated CCR1 preferentially recruited Gαi, which rarely affects the ERK kinase pathway, and that it inhibited STAT3 phosphorylation by upregulating ITPR3, which is essential for both immune activation and cancer pathogenesis." (PMID 36317881, 2022). "Likewise, treatment with betulinic acid considerably reduced the levels of p-STAT3 in MDA-MB-231 and 4T1 cancer cells." (PMID 36615262, 2022). "STAT3 is not only a downstream target of IL-6, but, along with miR-181b-1, miR-21, PTEN and CYLD, lysine 63 deubiquitinase is part of the positive feedback loop regulating the epigenetic switch linking inflammation to cancer." (PMID 36010971, 2022). "In previous function assays, OCIAD2 was shown to be essential for the activation of signal transducer and activator of transcription 3 and cell migration, which suggested that OCIAD2 may contribute to the metastasis of cancer cells." (PMID 35768832, 2022). "Interestingly, IL-6 has been demonstrated to switch on the JAK/STAT3 pathway and enhance EMT, which in turn promotes cancer proliferation, metastasis, and chemoresistance." (PMID 35681689, 2022). "Conversely, Stat3β, generated by alternative splicing and lacking the C-terminal transactivation domain, inhibits cancer progression, acting as a repressor of Stat3." (PMID 35681623, 2022). "The JAK/STAT3 and TGF-β/SMAD signalling pathways play critical roles in regulating cancer cell metastasis and can synergistically enhance EMT and the metastatic ability of cancer cells." (PMID 35655269, 2022). "In ovarian cancer and myeloproliferative neoplasm, PBX1 has been shown to participate in maintaining cancer stem cell-like phenotypes and promoting platinum resistance, at least partially, through its intricate interaction with the JAK2/STAT3 signaling network." (PMID 36361531, 2022).
cancer (continued). "Though the in vitro anti-cancer activity of napabucasin does not depend on STAT3 inhibition, it is possible that inhibition of this pathway has in vivo effects." (PMID 35267638, 2022). "The STAT3 pathway has been demonstrated to cause muscle atrophy in DMD, Merosin-negative congenital muscular dystrophy (MDC1A), sepsis, and cancers." (PMID 35565236, 2022). "As let-7a is a known regulator of many oncogenes, including Myc, Ras, HMGA, JAK, STAT3, and NIRF, our discovery that let-7 miRNAs regulate AKT1 phosphorylation makes them exciting new targets for the development of chemotherapeutics in AKT1-derived cancers." (PMID 35269443, 2022). "Besides, ZQL-4c significantly inhibited the expression of phospho-STAT3 and phospho-JAK2 in three types of cancer cells." (PMID 35528507, 2022). "For example, cancer stem cell-derived extracellular vesicles (CSC-EVs) promoted chemoresistance, stemness, and the metastatic potential of oral cancer cells by enhancing PI3K/mTOR/STAT3 signaling." (PMID 36231093, 2022). "The CD163/IL‐6/Stat3 pathway is suggested to be critical in protumor TAMs, however, macrophage‐mediated cancer cell proliferation was not affected by anti‐IL‐6R antibody (unpublished data)." (PMID 35132816, 2022). "Interestingly, inflammatory cytokines also activate the Janus kinase (JAK)–signal transducer and activator of transcription 3 (STAT3) pathway, with an induction of STAT3 phosphorylation observed in cancer." (PMID 36251564, 2022). "In our study, five DEPs (CD44, Stat3, CAMK2D, CAMK2B and CAMK2G) were identified in the proteoglycans in cancer signaling pathway, which worked together to modulate functions of this pathway, such as cell migration and invasion, cell adhesion, cell growth and survival." (PMID 36678534, 2022). "The aberrant activation of STAT proteins, most particularly STAT1, STAT3 and STAT5, has been suspected or proposed to significantly contribute to the progression of a variety of human tumors and cancer cell lines, including hematologic malignancies and solid tumors." (PMID 35163491, 2022). "There is increasing evidence that STAT3 and NRF2 have synergistic effects in cancer cells." (PMID 36557902, 2022). "STAT3 is constitutively activated in cancer cells, unlike normal cells where it is strictly regulated." (PMID 35769912, 2022). "It has been claimed that myeloid-derived suppressor cells (MDSCs), which are precursors of DCs, macrophages, or granulocytes, have the ability to negatively regulate the immune response in cancer, with a subpopulation of monocytic MDSCs mediated by the EPOR-mediated Jak2/GATA3/STAT3 pathway induced." (PMID 35359375, 2022). "By limiting the activity of STAT3, SSD is crucial in preventing cancer." (PMID 36547471, 2022). "Indeed, cancer-promoting proteins, such as the EML4-ALK fusion protein, appear to activate STAT3 in the nucleus by novel interactions with STAT3 at the level of such phase-separated nanodroplets." (PMID 35406728, 2022). "A recently published review did not mention variants in DN-STAT3 as possible triggers of monogenic adult-onset IEI, unlike STAT3 gain-of-function (GOF) mutations, which have been reported to induce immune dysregulation and predispose adults to cancer." (PMID 36605204, 2022). "Additionally GH assists cell motility and invasion, as well as, acquiring cancer stem cell-like criteria of HCC cells, by inhibiting another tight junction protein called Claudin-1 through activation of STAT3 in HCC." (PMID 36374927, 2022).
cancer (continued). "Based on these results, the authors concluded that UA has anticancer activity dependent on STAT3 signaling, that STAT3 acts as a bridge between EGFR and PD-L1 and that UA may be a drug candidate for PD-L1-based targeted cancer therapies." (PMID 36364289, 2022). "Several known drugs that were not initially used in cancer treatment have shown significant anti-cancer activity by targeting the STAT3 signaling pathway." (PMID 36559280, 2022). "Drug-targeted activation of STAT3 and STAT5 has been an active subject of cancer studies." (PMID 33968766, 2021). "BCAR4 via miR-665/STAT3 axis could promote tumorigenicity in CCR and maintains cancer stem cell stemness." (PMID 34368145, 2021). "Importantly, patients with PTC cancers who had increased glucose uptake assessed by 18FDG PET scans displayed lower levels LINC00671 and higher levels of STAT3 and LDHA expression." (PMID 34404767, 2021). "As the most focused mRNA, while considering the crosstalk between ceRNA network mediated STAT3 regulation and ferroptosis, evidence was only reported in cancers but not in HF." (PMID 34692796, 2021). "In addition, STAT proteins are known to be involved in cancer tumorigenesis and the promotion of cancer development, and among STAT proteins, STAT3 is known to induce EMT." (PMID 34445405, 2021). "In addition to its role in the regulation of gene expression, miR-1290 can regulate activity of JAK/STAT3, PI3K/AKT, Wnt/β-catenin and NF-κB signaling pathways, thus influencing several cancer-related routes." (PMID 35004844, 2021). "Interestingly, TRIM6 expression was positively correlated with several cancer-related pathways, including NF-κB, CTNNB1, and STAT3 signaling." (PMID 34589421, 2021). "IL-6 delivers signals through the STAT3 pathway, and recent studies have reported that CD36 is a downstream target of activated STAT3, suggesting that upregulation of IL-6 expression would further increase the uptake of FAs by cancer cells." (PMID 34722305, 2021). "Cellular studies carried out on a panel of cancer cell lines contributed to elucidating β-HCH’s activation pathways, identifying the protein STAT3 (Signal Transducer and Activator of Transcription 3) as the main modulator in the molecular responses induced by this organochlorine." (PMID 34072471, 2021). "Among these miRNAs, miR-21 has been extensively investigated in different cancers where it was shown to target important tumor suppressors such as, for example, PTEN, SPRY2, TIMP3, PDCD4, RECK, and STAT3, and thus to behave as one of the most important oncogenic miRNAs (oncomiR) identified to date." (PMID 34638467, 2021). "IL‐6/STAT3 signalling upregulates the expression of genes involved with cell proliferation (c‐Myc and cyclin D1), angiogenesis (VEGF) and the inhibition of apoptosis (Bcl‐xL and survivin) in cancers." (PMID 33382511, 2021). "Altogether, our data suggest a role for PSMD1, PSMD3, and STAT3 in regulating NF-κB expression and activity in CML and TKI resistance, and implicate them as potential targets for the treatment of hematologic malignancies and possibly other forms of cancer." (PMID 33712704, 2021). "The results revealed that angiogenesis, glycolysis, and EMT were the biological process most correlated with CD44 expression, while the TNFα signaling via NFκB, angiogenesis, IL6_JAK_STAT3 pathway, and EMT were correlated with TNFRSF12A in cancer cells across CRC, LC, and SCC." (PMID 34676217, 2021). "In the pathogenesis of cancer, elevated IL‐6 and IL‐27 could stimulate the activation of JAK1 and JAK2 enzymes, which subsequently mediate tyrosine phosphorylation of STAT3 at Tyr705." (PMID 33277798, 2021). "In TNBC and other cancers, the ID oncogenic transcripts foster diverse cancer-related events, including EMT, signaling (e.g., EGFR/TGF-beta, K-Ras, WNT, STAT3, PI3K/Akt, OCT-4/ID1/NF-kappaB), where ID genes are a target of many anticancer drugs, including vinblastine." (PMID 34299315, 2021).
cancer (continued). "Although STAT3 is often considered an important player in cancer immunotherapy, it was not selected as top biomarker in our analysis." (PMID 34430923, 2021). "Our results suggest that 13R,20-diHDHA deregulates the dynamic equilibrium from non-stem cancer cells to CSCs by dephosphorylating Stat3 and decreasing IL-6 secretion, thereby inhibiting CSC formation." (PMID 33804152, 2021). "Then, we applied STAT3 inhibitor S3I-201 to explore whether STAT3 activation and the nuclear translocation of p-STAT3 have effects on the PAR1 activating-induced cancer promoting effect." (PMID 34844621, 2021). "Generally speaking, cancer stem cell maintenance by LIF and LIFR seem to follow a similar trend as that seen in mESCs: LIF signaling leads to the activation of STAT3, which increases the stem cell like properties in solid tumors through transcriptional regulators." (PMID 34395259, 2021). "STAT3 overexpression substantially increased the migration and invasion of HepG2 cells with KIAA1217 silencing, as evidenced by the wound-healing assay, transwell migration assay, and cancer cell spheroid invasion assay in a 3D setting." (PMID 35008530, 2021). "HCC is a typical example of an inflammation related cancer where increased IL-6 and TNFα may be responsible for the activation of JAK/STAT3 signaling." (PMID 34639131, 2021). "Besides, constitutively activated STAT3 can also upregulate the expression of anti‐apoptotic genes, including BCL-XL and MCL-1, in human cancer cells." (PMID 34354046, 2021). "It is well known that NF-κB and STAT3 signaling plays an essential role in cell growth, differentiation, apoptosis, and previous study revealed that SHMT2 is a new player in STAT3 signaling in cancer." (PMID 34149818, 2021). "In addition, it has been shown that Sp1 and STAT3 are transcription factors that regulate VEGF expression and VEGF secretion of cancer cells." (PMID 34458134, 2021). "Results show that the level of LEPROT was consistently positively correlated with that of JAK1, JAK2, and STAT3, which suggested that JAK1/2/STAT3 might be the downstream LEPROT and mediate cancer cell proliferation and TME alterations." (PMID 34804118, 2021). "In this cancer model, SIRT6 restoration led to apoptosis through upregulation of Bax and cleaved caspase-8, along with downregulation of Bcl-2 and inhibition of the JAK2/STAT3 pathway." (PMID 33800266, 2021). "Saha and co-workers observed that cancer prostate cell lines (human PC3; DU145; LNCaP and murine HMVP2) treated with 6-shogaol, showed decreased levels of several signal transducer and activator of transcription 3 (STAT3) and NF-κB-regulated target genes including cyclin D1." (PMID 34202966, 2021). "Further, they reported that malignant cells with constitutively active STAT3, treated with RES, showed irreparable cell cycle arrest at the G0-G1 phase or the S phase of several cancer cell lines, including human breast (MDA-MB-231) cell line, as well as apoptosis, leading to loss of viability." (PMID 34488773, 2021). "Among, 10953 patients/10967 samples of all type of human cancers publicly available in the online cancer genomic database cBioPortal, genetic alterations of CDK2/4/6 and STAT3 occurs in 825 (8%) patients, comprising 127 (1.2%) CDK2, 307 (2.8%) CDK4, 266 (2.4%) CDK6, and 220 (2%) STAT3 and." (PMID 33668805, 2021). "In addition to the C‐MET/STAT3 cascade, both AKT/mTOR and MAPK pathways can mediate the aberrant growth and apoptosis resistance of cancer cells." (PMID 34586726, 2021). "Hence, our data provide evidence that expressions of CDK2/4/6 and STAT3 can be directly regulated by NSC765690 and NSC765599 with consequent antitumor implications in multiple cancer types." (PMID 33477856, 2021). "Mounting evidence implicates STAT3 and MAPK signaling in cancer cell proliferation and apoptosis." (PMID 34760885, 2021).
cancer (continued). "In addition, Sohl and colleagues used in vivo and in vitro binding assays to prove that the V561M mutant strongly activated STAT3 and produced significant resistance to AZD4547, thereby driving cancer progression." (PMID 33568192, 2021). "Signal transducer and activator of transcription 3 (STAT3) is an important transcription factor involved in many physiological functions including embryonic development and immune responses and is often activated under pathological conditions such as cancer." (PMID 33839684, 2021). "Likewise, Stattic (a STAT3 phosphorylation inhibitor) deactivates STAT3 and suppresses CCL16 expression, thereby decreasing CCL16-mediated cancer cell stemness." (PMID 33500726, 2021). "STAT3 is essential for the maintenance of a stem cell phenotype, and accumulating evidence suggests that TLR signaling is also important in undifferentiated epithelial cells and cancer stem-like cells (CSC) because of the downstream NF-kB activity." (PMID 35048056, 2021). "Thus, we propose that activated STAT3 regulates XRCC1 under stress and growth conditions, but constitutive activation in cancers results in dysregulation of XRCC1 and subsequently BER and SSBR." (PMID 34067421, 2021). "There has been a significant focus throughout the years on STAT3 being the causal driver of LIF mediated effects in cancer, and not without cause—our primary understanding of LIF is derived through its effects on mESCs via STAT3." (PMID 34395259, 2021). "This novel signaling pathway in between fibrogenic PSCs and cancer cells in the TME of PDAC could present a possible therapeutic approach to prevent fibrosis and STAT3 activation through P2X7R inhibition as well as IL-6R neutralization by Tocilizumab." (PMID 34440697, 2021). "These LOF TYK2 variants failed to phosphorylate STAT3 in cells in vitro, and further support the immunosurveillance role of TYK2 in cancer." (PMID 34439323, 2021). "Hyperactivation of STAT3 in both cancer cells and non-cancerous cells within the TME is observed in most human malignancies; its association with poor patient outcome has also been reported." (PMID 34063828, 2021). "Some of the key TFs that act as drivers of cancers include NF-kB, HIF1, C-Myc, AP-1, STAT3, etc.." (PMID 34572488, 2021). "On the other hand, STAT1, found down-regulated in the same cell lines, as opposed to STAT3, elicits pro-apoptotic and anti-proliferative responses and promotes anti-cancer immunity." (PMID 33898418, 2021). "The consequence revealed that the high- and low- METAscore groups exhibited distinct mutation characteristics and the genes with a high mutation frequency in TTN, MUC4, PIK3CA, and MUC16 which all correlated with EMT and critical cancer pathways including PI3K/AKT and JAK2/STAT3 in CESC." (PMID 34277697, 2021). "The PI3K/Akt, Wnt, STAT3, NF-κB and Sonic signaling pathways undergo down-regulation by natural products to reduce expression level of CSC markers including CD44, CD133, Notch, Oct4 and Nanog, impairing cancer stemness and progression." (PMID 34769099, 2021). "It is well known that various stimuli such as growth factors, cytokines, and oncogenic proteins can induce STAT3, so it is not surprising that this TF can be differently activated in response to the treatment of cancer cells with IR." (PMID 34141616, 2021). "STAT3 can also regulate the activation of key transcription factors such as Snail and Twist which mediate the epithelial-mesenchymal transition (EMT) process, and in turn, metastasis of cancer cells to the distant organs." (PMID 34771643, 2021).